MAVS (mitochondrial antiviral signaling protein)
Diseases named in the same sentence as MAVS in open-access papers (continued):
Sharing a sentence is not in itself a finding about the gene and the disease.
enterovirus infection (6 papers, 2017 to 2025). "MDA5 and MAVS cleavage during enteroviral infections has been associated mainly to 2Apro, though cleavage of overexpressed MAVS by 3Cpro has also been shown." (PMID 28660175, 2017). "In this study, we constructed a cell-based fluorescent reporter system to visualize enterovirus infection by taking advantage of the feature of MAVS cleavage by viral protease." (PMID 37243150, 2023). "Deletion of MAVS or its upstream sensor MDA5 in mice was shown to increase viral replication and decrease survival of CVB3-infected mice, suggesting an antiviral defense role for MAVS against enteroviral infection." (PMID 36851568, 2023). "In enterovirus infections, several proteins in the RLR signaling pathway are cleaved and/or degraded, such as RIG-I, MDA5, and MAVS." (PMID 37555661, 2023). "Enterovirus infection induces the cleavage or degradation of host factors, including RIG-I, MDA5, MAVS, TRIF, and IRF7/9." (PMID 35782136, 2022).
glioma (6 papers, 2020 to 2024). A benign or malignant brain and spinal cord tumor that arises from glial cells (astrocytes, oligodendrocytes, ependymal cells). "We also showed that IFN receptor (e.g., IFNAR1) and ISGs (e.g., EIF2AK2 and MAVS) were prognostic and editing-regulated in glioma." (PMID 35406793, 2022). "Recent studies show that MAVS can promote a neuroinflammatory tumor microenvironment and is a potential therapeutic target in glioma treatment." (PMID 35850307, 2022). "Our data showed that ectopic expression of RIG-I, MDA5, MAVS, or TBK1 was not sufficient to inhibit the elevated replication of VSVΔ51 induced by D2HG in glioma cells." (PMID 37880243, 2023).
multiple sclerosis (6 papers, 2016 to 2022). A progressive autoimmune disorder affecting the central nervous system resulting in demyelination. "The interaction of MAVS with cytosolic phospholipase A2 (cPLA2) promotes a proinflammatory transcriptional program associated with pathogenesis in neurologic diseases such as experimental autoimmune encephalomyelitis and multiple sclerosis." (PMID 35850307, 2022). "Recently, astrocytic activation of cPLA2 bound directly with MAVS enhanced NF-ĸB pathways to produce proinflammatory factors such as Ccl2 and Nos2 in an animal model of multiple sclerosis (MS)." (PMID 35705959, 2022). "Moreover, MAVS-mediated nuclear factor kappa B (NF-κB) activation also promoted neuroinflammation in experimental autoimmune encephalomyelitis (EAE) and multiple sclerosis (MS)." (PMID 35844503, 2022).
asthma (4 papers, 2018 to 2024). "The purpose of this study was to analyze the effects of NLRP3 and MAVS polymorphisms on the risk of asthma and the interactions between them." (PMID 36595748, 2022). "Interactions between NLRP3 and MAVS polymorphisms may affect the risk of asthma." (PMID 36595748, 2022). "There may be interactions between NLRP3 and MAVS polymorphisms in the risk of asthma." (PMID 36595748, 2022). "The epithelial alarmin TSLP induces the expression of CUL5, which then interacts with and degrades OGT via K48-linked ubiquitination, inhibiting MAVS O-GlcNAcylation and IFN-β production, and eventually inducing asthma exacerbations." (PMID 38177117, 2024). "The distribution of NLRP3 rs10925023/MAVS rs7272495 haplotypes frequencies between asthma group and control group [n (%)]." (PMID 36595748, 2022). "In conclusion, the MAVS rs6515831 and NLRP3 rs10925023 polymorphisms were associated with the risk of asthma in children." (PMID 36595748, 2022). "The MAVS rs6515831 and NLRP3 rs10925023 polymorphisms were associated with the risk of asthma in children." (PMID 36595748, 2022). "The function of NLRP3 and MAVS needs to be confirmed by further research and it is helpful to deeply understand asthma." (PMID 36595748, 2022). "Further research will be required to identify the role played by theese regulatory receptors of ITAM or MAVS‐RIGI pathway of pDCs in the pathogenesis of asthma." (PMID 33236850, 2021). "Given the role of OGT-mediated MAVS O-GlcNAcylation in the CUL5-mediated inhibition of antiviral immunity in vitro, we investigated the role of OGT in CUL5-mediated asthma exacerbations in vivo." (PMID 38177117, 2024).
cardiac insufficiency (4 papers, 2022 to 2025). "Research indicates that abnormal activation or dysregulation of MAVS may be associated with various cardiovascular diseases, including myocarditis, heart failure, and myocardial infarction." (PMID 40842475, 2025). "We will first review the basic functions of MAVS in innate immunity, then conduct an in-depth analysis of the specific roles of MAVS in different types of cardiovascular diseases, including viral myocarditis, heart failure, and myocardial infarction." (PMID 40842475, 2025). "While MAVS is well-known for its role in antiviral immunity and various other immune responses, some studies have documented its involvement in viral myocarditis, cardiac insufficiency and CVD." (PMID 40040697, 2025). "This study broadens our knowledge of the pathogenesis of cardiac insufficiency and may provide therapeutic potential by targeting MAVS." (PMID 35844503, 2022).
co-infection (4 papers, 2014 to 2025). "However, in the MAVS-/- mice, CL caused by either L. major infection or L. major-SFSV co-infection resulted in similar levels of inflammation, implicating MAVS in the increased CL severity caused by SFSV." (PMID 34310619, 2021). "Compared to FAdV-I single infection, the transcription levels of IFN-α and IFN-β along with MDA5, MAVS, and Mx decreased significantly after co-infection, suggesting a series of chain reactions." (PMID 37896849, 2023). "As a critical viral PRR adaptor protein, we were interested in the possible role of MAVS, and RIG-I by association, in the hyperinflammation caused by SFSV and L. major co-infection." (PMID 34310619, 2021). "Here, we determined that SFSV co-infection with L. major results in a greater parasite load in infected mice, which manifests through an exacerbated form of CL; ostensibly, this aggravated CL is the result of a host immunopathological response that occurs through TLR3- and MAVS-dependent pathways." (PMID 34310619, 2021). "In absence of coinfection, HCV infection usually down-regulates NF-κB activation directly via viral proteins such as HCV Core or indirectly through inactivation of the MAVS (mitochondrial antiviral signaling) protein." (PMID 24809719, 2014).
experimental autoimmune encephalomyelitis (4 papers, 2020 to 2022). An autoimmune demyelinating disease of the central nervous system that is produced experimentally in animals by the injection of homogenized brain or spinal cord in Freund's adjuvant. "Sphingolipid metabolism in astrocytes has been reported to trigger cPLA2 recruitment to mitochondrial antiviral signaling protein (MAVS), boosting NF-κB–driven transcriptional programs that promote inflammation in experimental autoimmune encephalomyelitis." (PMID 34491907, 2021).
glioblastoma (4 papers, 2016 to 2023). The most malignant astrocytic tumor (WHO grade IV). "Owing to the known biological intersection of innate immunity, ADARs, and dsRNA, the identification of MAVS as an ADAR3-bound transcript that exhibits reduced editing in ADAR3-expressing glioblastoma cells drew our attention." (PMID 35850307, 2022). "Together, these data indicate that MAVS is a target of ADAR3 in glioblastoma cell lines." (PMID 35850307, 2022). "Altogether, this study provides the first global view of ADAR3-bound RNAs in glioblastoma cells and identifies both a role for ADAR3 in repressing ADAR1-mediated editing and an RNA-binding dependent function of ADAR3 in regulating MAVS expression." (PMID 35850307, 2022). "Herein, our results add to the complex gene regulation of MAVS by revealing a unique role for ADAR3 binding to the MAVS transcript and upregulating MAVS protein expression in glioblastoma cells, independent of the editing levels within the MAVS 3′ UTR." (PMID 35850307, 2022). "In glioblastoma (GBM), ADAR3 inhibits ADAR1-mediated editing in the MAVS 3’ UTR which induced upregulation of MAVS protein level without impacting MAVS mRNA expression." (PMID 37662910, 2023).
malaria (4 papers, 2016 to 2022). Malaria is a serious and sometimes fatal disease caused by a parasite that commonly infects a certain type of mosquito which feeds on humans. "STING recognizes AT-rich DNA motifs from malaria parasites, whereas MDA5/MAVS can detect parasite RNAs from both sporozoite and blood stages." (PMID 27716849, 2016).
myocarditis (4 papers, 2017 to 2025). Myocarditis is a condition that is characterized by inflammation of the heart muscle (myocardium). "In the absence of MAVS signaling, persistent infection leads to focal myocarditis and vasculitis of the large vessels attached to the base of the heart." (PMID 37537212, 2023). "Impaired MAVS signaling may enable continued viral replication, leading to myocarditis and vascular inflammation." (PMID 40862416, 2025). "Overall, our results show that a robust IFN-I response and MAVS signaling are required to control CHIKV infection in the heart and prevent focal myocarditis as well as Ao and PA vasculitis." (PMID 37537212, 2023). "Our results indicate that TRIM21 inhibits CVB3 replication via interacting with MAVS for promoting the K27 polyubiquitination of MAVS, thereby enhancing IRF3-mediated type I IFN signaling pathway and protecting mice against CVB3-induced myocarditis as well as pancreatic acinar cell necrosis." (PMID 30410495, 2018).
bladder cancer (3 papers, 2017 to 2025). "We have discovered a novel variant of WT rat MAVS in the NBT-II rat bladder cancer cell line, designated as ‘MAVS500’." (PMID 39858533, 2025). "In bladder cancer cells, DAC treatment increased the double-stranded RNA sensors, MDA5, MAVS and RIG-1, intermediate mediator IRF7, and downstream targets IFI44 and IFI27 and IFN-γ by 2-fold to 70-fold compared to control cells." (PMID 29242529, 2017).
encephalitis (3 papers, 2024 to 2025). An acute inflammatory process affecting the brain parenchyma. "Thus, MAVS signaling potentially affects the microglia function of cross-presenting antigen to antigen-specific T cells, which recently was proposed to be a hallmark of microglia during viral encephalitis." (PMID 40619428, 2025). "Taken together, our results highlight MAVS-dependent induction of the antigen presentation machinery of long-lived CX3CR1+ CNS cells such microglia as a novel critical mechanism of microglia-CD8+ T cell interaction during viral encephalitis." (PMID 40619428, 2025). "Immune-related genes such as mitochondrial antiviral-signaling protein (MAVS), natural cytotoxicity triggering receptor 2 (NCR2), and IL-10 seem to be involved in the WNV onset of encephalitis." (PMID 40266979, 2025). "Overall, these data indicate that MAVS signaling of immune cells infiltrating the infected CNS is not needed for protection against viral encephalitis, but MAVS signaling of brain-resident cells is critical." (PMID 40619428, 2025). "Importantly, upon MAVS deletion we did not detect impaired infiltration with CD8+ T cells, further supporting the concept that MyD88-dependent chemokine responses drive T-cell infiltration during viral encephalitis." (PMID 40619428, 2025).
fungal infections (3 papers, 2021 to 2023). "The MAVS protein has been identified as the major protein implicated in innate signaling against bacterial and fungal infections." (PMID 35174241, 2021). "OTUD1 regulated the production of antiviral cytokines and inflammatory cytokines by MAVS/TRAF3/TRAF6 signaling or NF-κB signaling cascades during viral and fungal infections." (PMID 38012669, 2023).
gastric cancer (3 papers, 2020 to 2024). A primary or metastatic malignant neoplasm involving the stomach. "MAVS puncta formation was also evident in lytic EBV+ gastric carcinoma AGS cells." (PMID 37311461, 2023).
HCMV infection (3 papers, 2016 to 2023). "Consistent with in vitro data, HCMV infection shows that US9 is an important viral factor for promoting the reduction of mitochondrial MAVS expression and STING–TBK complexes, disrupting IRF3 nuclear translocation, and consequently inhibiting IFN-β production." (PMID 29317664, 2018). "In this study, we found that HCMV infection caused mitochondrial fusion, and expression of mitofusin 1 (MFN1), which is a protein associated with mitochondrial antiviral signaling protein (MAVS), positively regulates mitochondrial fusion and HCMV-induced IFN1 response." (PMID 36939338, 2023). "In the present study, human monocytic macrophage THP-1 was used as cell model for HCMV infection and changes in interferon signal pathway and mitochondrial morphology, MFN1, and MAVS were detected." (PMID 36939338, 2023). "In this study, we identify the first HCMV glycoprotein US9 as the suppressor of MAVS and STING-mediated signaling to inhibit IFN-β production and antiviral responses during late stages of HCMV infection." (PMID 29317664, 2018). "In addition, the redistribution of MAVS was induced by HCMV infection, whereas the knockdown of MFN1 inhibited the redistribution of MAVS and disrupted the interferon signaling pathway." (PMID 36939338, 2023). "Indeed, our findings in vitro and in vivo support that US9 facilitates MAVS degradation, disrupts the STING–TBK1 signaling axis, and impedes phosphorylated IRF3 into the nucleus during HCMV infection, resulting in inhibition of IFN-β expression." (PMID 29317664, 2018).
hepatitis C (3 papers, 2014 to 2015). "Retinoic acid inducible gene I (RIG-I) is a viral RNA sensor crucial in defense against several viruses including measles, influenza A and hepatitis C. RIG-I activates type-I interferon signalling through the adaptor for mitochondrial antiviral signaling (MAVS)." (PMID 24466302, 2014). "To identify components that regulate MAVS signalosome assembly on the MAM, we characterized the proteome of MAM, ER, and cytosol from cells infected with either chronic (hepatitis C) or acute (Sendai) RNA virus infections, as well as mock-infected cells." (PMID 25734423, 2015).
lentivirus infection (3 papers, 2010 to 2017). Virus diseases caused by the Lentivirus genus. "Of note, lentivirus infection reduces the difference of γHV68 plaque forming capacity in wild-type MEFs and in MEFs deficient in MAVS and IKKβ." (PMID 20686657, 2010). "When exogenous MAVS and IKKβ were re-introduced by lentivirus infection, γHV68 infection induced a transient RelA degradation, bolstering the specific requirement for MAVS and IKKβ in RelA degradation triggered by γHV68 infection." (PMID 22110409, 2011).
psoriasis (3 papers, 2019 to 2024). An autoimmune condition characterized by red, well-delineated plaques with silvery scales that are usually on the extensor surfaces and scalp. "Targeting MAVS orTLR3 in KC to prevent IFNβ production from the skin epidermis is of great potential for future targeted therapy development to treat psoriasis." (PMID 31293591, 2019).
reovirus infection (3 papers, 2015 to 2022). "Next, we investigated if overexpression of PARP9 could induce type I IFN production in PARP9 and MAVS DKO BMDC after sensing dsRNA or reovirus infection." (PMID 33976210, 2021). "Although we did not observe a difference in activation of the IFN response by mito- or pexMAVS in various cell lines and experimental approaches, Dixit and colleagues described a rapid, type I IFN-independent signaling of pexMAVS in MAVS-/- MEFs after reovirus infection." (PMID 26588843, 2015). "Compared to WT BMDC, PARP9 KO or MAVS KO or both PARP9 and MAVS DKO reduced dramatically production of IFN-α and IFN-β in PARP9 KO or MAVS KO BMDC in response to stimulation with intracellular poly (I:C) or reovirus infection." (PMID 33976210, 2021). "For example, the expression of ISGs is mainly dependent on peroxisome-localized MAVS rather than mitochondria-localized MAVS during reovirus infection." (PMID 36148221, 2022). "As expected, overexpression of PARP9 in PARP9 and MAVS DKO BMDC produced significantly more IFN-α and IFN-β than those cells expressing control vector in response to intracellular poly I:C or viral dsRNA Reo1198 or reovirus infection." (PMID 33976210, 2021). "Compared to PARP9 and MAVS DKO BMDC, MAVS KO produced significantly more IFN-α and IFN-β in response to stimulation with intracellular poly (I:C) or reovirus infection." (PMID 33976210, 2021). "Furthermore, we examined the phosphorylation of IRF3 and NF-κB subunit p65 in WT, PARP9 KO, MAVS KO, and PARP9/MAVS DKO BMDC after reovirus infection." (PMID 33976210, 2021). "However, overexpression of PARP9 in PARP9 and MAVS DKO BMDC did not affect the IL-6 production in response to intracellular poly I:C or viral dsRNA Reo1198 or reovirus infection." (PMID 33976210, 2021). "Additionally, MAVS KO or both PARP9 and MAVS DKO abrogated IL-6 production in response to intracellular poly I:C or reovirus infection, while PARP9 KO did not affect IL-6 production compared to WT BMDC." (PMID 33976210, 2021). "Knockdown of either PARP9 or MAVS reduced the production of IFN-α and IFN-β in human MDDC in response to LPIC or reovirus infection, but not to dsDNA HSV-60 or cGAMP treatment." (PMID 33976210, 2021).
Rotavirus infection (3 papers, 2013 to 2023). Infection with any of the rotaviruses. "Rotavirus VP3 protein targets mitochondria and mediates the phosphorylation of the SPLTSS motif in the proline-rich region of MAVS, causing MAVS to be degraded through the proteasome pathway, blocking the production of IFN-γ during Rotavirus infection of intestinal epithelial cells." (PMID 33923929, 2021).
Sepsis (3 papers, 2014 to 2026). Sepsis is defined as life-threatening organ dysfunction caused by a dysregulated host response to infection. "By using additional gene targeted deletion mice, we show that WNV infection triggered signaling through the RIG-I like receptor adaptor protein MAVS to cause complement activation, sepsis, and tissue damage." (PMID 24743949, 2014). "Moreover, cross-cohort and cross-tissue analysis identified eight key genes with dysregulated RNA editing during sepsis, particularly mitochondrial antiviral-signaling protein (MAVS), whose RNA editing was significantly downregulated." (PMID 41852687, 2026).
viral myocarditis (3 papers, 2012 to 2025). Myocarditis that is caused by an infection with a viral agent. "This review highlights recent progress in understanding the contributions of MAVS in viral myocarditis, ischemic myocardial damage, hypertrophic cardiomyopathy and other cardiomyopathy." (PMID 40040697, 2025). "Another research found metalloproteinase domain 9 (ADAM9) bind to MDA5 and promoted (MAVS), and thereby induced type I interferon production during encephalomyocarditis virus infection, which provides a therapeutic target for viral myocarditis." (PMID 40040697, 2025). "MAVS is extremely important for the development of viral myocarditis." (PMID 40842475, 2025). "Thus, deficiency or decrease of MAVS may result in non-clearance of CVB3 and the subsequent tissue necrosis, viral persistence or immunopathologic damage, with a latent possibility of CVB3 related symptoms such as viral myocarditis." (PMID 23249700, 2012).
acute monocytic leukemia (2 papers, 2022 to 2023). Acute monoblastic leukemia (AML-M5), is one of the most common subtypes of acute myeloid leukemia (AML) that is either comprised of more than 80% of monoblasts (AML-M5a) or 30-80% monoblasts with (pro)monocytic differentiation (AML-M5b). "SeV infection induces the activation of MAVS signaling by promoting NLRP3-dependent caspase-1 activation, whereas knockdown of MAVS expression significantly attenuated the NLRP3 inflammasome in human acute monocytic leukemia cells (THP-1) and mouse macrophages." (PMID 36560803, 2022).